FGF19 (fibroblast growth factor 19)
Diseases named in the same sentence as FGF19 in open-access papers (continued):
Sharing a sentence is not in itself a finding about the gene and the disease.
Glucose intolerance (8 papers, 2014 to 2023). Glucose intolerance (GI) can be defined as dysglycemia that comprises both prediabetes and diabetes. "Administration of recombinant FGF19 protein prevented the development of glucose intolerance in both high-fat-fed mice and leptin-deficient mice." (PMID 28729691, 2017). "In agreement with previously published data using obese rodent models, we found that FGF19 did ameliorate glucose intolerance induced by CKD." (PMID 37015932, 2023). "It was shown that FGF-19 transgenic mice were resistant to glucose intolerance and hyperinsulinemia induced by a high-fat diet (HFD)." (PMID 36362225, 2022). "In this study, we highlighted the link of CDCA with FGF19 in Chinese subjects with different degrees of glucose intolerance." (PMID 28729691, 2017). "We show that FGF19-induced signaling in the hypothalamus ameliorated glucose intolerance by improving insulin sensitivity." (PMID 24567901, 2014). "Furthermore, FGF19 treatment attenuated glucose intolerance and reduced hepatic expression of gluconeogenic genes in uremic mice." (PMID 37015932, 2023). "In addition, Fgf15 deletion results in glucose intolerance, while FGF19 transgenic mice displayed reduced glucose levels and improved insulin sensitivity." (PMID 24567901, 2014). "Knockout mouse models for FGF15, the mouse ortholog of FGF19, and for FGF21 develop glucose intolerance and insulin resistance." (PMID 30374109, 2018).
chronic kidney disease (6 papers, 2013 to 2026). Impairment of the renal function secondary to chronic kidney damage persisting for three or more months. "In the end stage of chronic kidney disease, an impaired post-meal FGF19 response was observed, which was partially normalized by therapy with antioxidants." (PMID 30927227, 2019). "The kidney is clearly involved in the clearance of FGF19, as blood concentrations of FGF19 are higher in subjects with end stage renal disease." (PMID 24176017, 2013). "Recently, we showed that in a chronic kidney disease (CKD) model FGF19 significantly protects against muscle wasting and attenuates hepatic inflammation, but it fails to effectively protect against bone loss." (PMID 41185883, 2025). "In this context, it is noteworthy that high levels of FGF19 were found in non-diabetic patients with chronic kidney disease." (PMID 40869066, 2025). "Moreover, serum FGF19 levels are higher in patients with chronic kidney disease than in healthy controls, which may be related to the metabolism of lipids and carbohydrates, and hemodialysis and kidney transplantation can reduce the serum FGF19 level in patients with chronic kidney disease." (PMID 36927328, 2023).
coronary artery disease (6 papers, 2013 to 2020). "Of note, serum FGF19 concentration positively correlates with HDL-C levels, and lower FGF19 concentrations are associated with both the presence and severity of coronary artery diseases in humans." (PMID 30679232, 2019). "Despite these findings and the well-established link between metabolic disorders and cardiovascular disease, few clinical studies have reported on potential association of FGF19 with coronary artery disease (CAD)." (PMID 23940810, 2013). "Here, we investigated the association of FGF19 with the presence and severity of coronary artery disease (CAD) in a Chinese population." (PMID 23940810, 2013). "A recent study observed that plasma FGF-19 levels in patients with coronary artery disease (CAD) were reduced in the Chinese population and negatively related to the severity of CAD." (PMID 31443313, 2019). "In human, scientists have revealed a negative correlation between FGF19 and cardiovascular risk factors and found FGF19 as an independent factor of the development of coronary artery disease." (PMID 32528406, 2020). "Previous studies found that patients with coronary artery disease had lower levels of FGF19 compared to healthy controls, and FGF19 may be a protective factor for severe coronary artery disease." (PMID 32528406, 2020).
Crohn disease (6 papers, 2013 to 2022). A gastrointestinal disorder characterized by chronic inflammation involving all layers of the intestinal wall, noncaseating granulomas affecting the intestinal wall and regional lymph nodes, and transmural fibrosis. "Serum FGF19 levels are decreased in Crohn’s disease associated with diarrhea and disease activity, indicating that FGF19 has potential as a biomarker for the functioning ileum in Crohn’s disease." (PMID 26483756, 2015). "The risk of cholelithiasis is also increased in Crohn disease affecting the terminal ileum and following ileal resection; in these conditions, FGF19 deficiency as a consequence of intestinal mucosal inflammation or absence is likely to impair gallbladder function." (PMID 29876009, 2018). "However, FGF19 and FGF21 pathways (involved in Crohn’s disease and lipid metabolism, respectively) are mediated by β-Klotho, as opposed to α-Klotho." (PMID 34542150, 2022). "Inactive Crohn's disease was present in two patients, but neither of these patients had significantly different ileal FGF19 expression levels from the nine patients without Crohn's disease." (PMID 23518683, 2013).
depression (6 papers, 2023 to 2026). "Moreover, in patients with depression, a positive association was found between FGF19 levels and all clinical symptom scores, i.e., BDI-II, SAS, HAMD, and HAMA scores." (PMID 37266540, 2023). "ELISA validation confirmed that FGF-19, the sole protein significantly altered, was inversely correlated with depression scores and exhibited decreased expression in MD that was reversed by acupuncture." (PMID 41799812, 2026). "FGF-19's bidirectional expression profile positions a promising inflammation-related biomarker and a potential treatment-responsive marker for mild depression in young females, also an indicator of acupuncture efficacy." (PMID 41799812, 2026). "Recently, significant correlations were found between human CSF FGF19 levels and Beck Depression Inventory scores." (PMID 37266540, 2023). "This study aimed to investigate the role of FGF19 and FGF21 in MDD and to explore the possible pathogenic mechanism of metabolic and cognitive dysregulation in depression." (PMID 37266540, 2023). "The associations between FGF19 and FGF21 levels and clinical symptom scores of the total population, HCs, and patients with depression were analyzed separately." (PMID 37266540, 2023). "After adjusting for potential confounders, such as BMI and smoking, and correcting for multiple testing, four proteins remained significantly associated with depression: fibroblast growth factor 21 (FGF21), FGF19, Interleukin-6 (IL-6) and Interleukin-20 receptor subunit alpha (IL-20RA)." (PMID 39523673, 2024). "BAs modulate depression pathogenesis through FXR, LXRs, and TGR5 receptors, orchestrating neuroinflammation (via NF-κB/NLRP3 suppression), gut microbiota metabolism (via GLP-1/FGF19 regulation), and neural plasticity (via BDNF/CREB activation)." (PMID 40362260, 2025). "Correlation analysis between FGF19 and FGF21 levels and RBANS in depression." (PMID 37266540, 2023). "Correlation analysis between FGF 19 and PGC-1α/FNDC5 in depression." (PMID 37266540, 2023).
lung squamous cell carcinomas (6 papers, 2016 to 2024). "It has been found that the amplification of FGF4 and FGF19 was five times more frequent in smokers with lung squamous cell carcinoma (LSCC)." (PMID 39590120, 2024). "FGF19 is highly amplified in lung squamous cell carcinoma, which ranks the fourth in the frequency in all examined cancer types from the TCGA Pan-Cancer cohort." (PMID 32111983, 2020). "Our group has previously identified FGF19 as a prognostic marker and potential driver gene of lung squamous cell carcinomas (LSQ) in Chinese smoking patients." (PMID 32111983, 2020).
ovarian carcinoma (6 papers, 2018 to 2026). A malignant neoplasm originating from the surface ovarian epithelium. "FGF19 is highly amplified and overexpressed in ovarian cancer, and is associated with patients’ poor prognosis." (PMID 36751636, 2023). "In conclusion, our study illustrated that the underlying mechanisms of FGF19 in the regulation of cell autophagy and chemoresistance in ovarian cancer cells." (PMID 36751636, 2023). "Besides, FGF19 is intimately linked with ovarian cancer, particularly in high-grade serous ovarian cancer (HGSOC), where it is often amplified and overexpressed." (PMID 41328353, 2026). "We then transfected GFP-LC3 into ovarian cancers cells, and found that FGF19 downregulation and BIRB796 treatment decreased the formation of GFP-LC3 puncta, while FGF19 upregulation and IFN-γ treatment increased the formation of GFP-LC3 puncta." (PMID 36751636, 2023). "Here, CCK8 was used to detect the potential roles of FGF19-p38 MAPK axis on the anti-proliferation effect of cisplatin in ovarian cancer cells." (PMID 36751636, 2023). "We screened the expression profiles of FGF19 in several ovarian cancer cells, and found that FGF19 were over-expressed in multiple ovarian cancer cells, including HO8910pm and SKOV3-IP." (PMID 36751636, 2023). "From TCGA-OC, we found that the expression of FGF19 was significantly upregulated in ovarian cancer tissues." (PMID 36751636, 2023). "In this study, the roles of FGF19 in cell autophagy and therapeutic response of ovarian cancer cells were demonstrated." (PMID 36751636, 2023). "IFN-γ, a potential p38 MAPK activator, counteracted the inhibition of cell autophagy and the anti-proliferation effect of cisplatin induced by FGF19 knockdown in ovarian cancer cells." (PMID 36751636, 2023). "IHC was performed to explore the FGF19 level in 118 ovarian cancer tissues, 22 normal ovarian and 26 normal fallopian tube." (PMID 36751636, 2023). "In this study, we investigated the roles of FGF19 in the regulation of autophagy and chemotherapy response in ovarian cancer." (PMID 36751636, 2023). "FGF19 knockdown inhibited autophagy and decreased cisplatin resistance in ovarian cancer cells by decreasing phosphorylation of p38 MAPK." (PMID 36751636, 2023). "In this study, we found that FGF19 promotes cisplatin resistance in ovarian cancer cells by inducing autophagy." (PMID 36751636, 2023). "First, the analysis results from TNMplot database showed that the expression of FGF19 mRNA in ovarian cancer tissues was higher than that in normal tissues." (PMID 36751636, 2023). "Studies have demonstrated that silencing FGF19 inhibits autophagy in ovarian cancer cells." (PMID 41328353, 2026). "FGF18 was also highly expressed in malignant tissue as well as normal ovarian tissue, suggesting that FGF19 may be more ovarian cancer–specific compared with FGF18." (PMID 38273381, 2024). "High level amplification and expression of FGF19 were observed in ovarian cancer." (PMID 36751636, 2023). "Collectively, the overexpressed FGF19 in ovarian cancer could be utilized as a potential biomarker for prognosis." (PMID 36751636, 2023). "FGF19 might promote autophagy and cisplatin resistance of ovarian cancer cells by activating p38 MAPK pathway." (PMID 36751636, 2023). "In addition, the expression level of FGF19 in ovarian cancer samples was higher than that in normal samples." (PMID 36751636, 2023). "Moreover, the upregulated FGF19 can promote ovarian cancer proliferation and invasion by activating mitogen-activated protein kinase (MAPK) signaling pathway." (PMID 36751636, 2023). "Additionally, the cBioPortal database revealed FGF19 amplification in a variety of cancers and four ovarian cancer datasets." (PMID 36751636, 2023). "We found that FGF19 was amplified and overexpressed in ovarian cancer cells." (PMID 36751636, 2023). "FGF19 increases autophagy and chemoresistance in ovarian cancer by activating the p38 MAPK pathway." (PMID 36751636, 2023).
ovarian carcinoma (continued). "Accordingly, our study confirmed that high levels of FGF19 could promote cell autophagy and cisplatin resistance in ovarian cancer cells." (PMID 36751636, 2023). "In our analysis of 62 paraffin-embedded ovarian cancer tissues, we identified FGF19 amplification." (PMID 36751636, 2023). "This showed that FGF19 is highly amplified in ovarian cancer." (PMID 36751636, 2023). "Thus, the results confirmed that FGF19 might be a prognostic and therapeutic target of ovarian cancer." (PMID 36751636, 2023). "However, the relationship between FGF19 and autophagy in ovarian cancer is still unknown." (PMID 36751636, 2023). "However, the association between FGF19 and autophagy in ovarian cancer has not been investigated." (PMID 36751636, 2023). "However, the detailed roles of FGF19 in cell autophagy and chemoresistance in ovarian cancer have not been not fully clarified." (PMID 36751636, 2023).
primary sclerosing cholangitis (6 papers, 2015 to 2024). "Aldafermin (NGM282), an FGF19 engineered analogue, is mainly applied in clinical trial including NASH and primary sclerosing cholangitis." (PMID 35847588, 2022).
alcoholic hepatitis (5 papers, 2020 to 2024). Acute hepatitis resulting from ingestion of alcohol. "In a recent study, it was shown that the serum levels of FGF19 were significantly increased, and the hepatic expressions of the FGF19 gene were also induced in alcoholic hepatitis patients." (PMID 34572066, 2021). "Moreover, FGF19 can be secreted by cells from pathological liver tissue, such as cholestatic non‐cirrhotic and cirrhotic livers and livers from individuals with alcoholic hepatitis and HCC." (PMID 34816013, 2021). "Additionally, FGF19 is believed to play a role in alcoholic hepatitis." (PMID 34572066, 2021).
breast tumors (5 papers, 2012 to 2026). "Consistently, FGFR4/FGF19 co-expression was also observed in 82 out of 287 (28.6%) primary breast tumors, and their expression is strongly associated with AKT phosphorylation, Ki-67 staining, higher tumor stage and basal-like phenotype." (PMID 27192118, 2016). "Genetic knockout of FGF19 or inhibition of FGFR4 has been demonstrated to inhibit breast tumor progression and metastasis in mouse models, suggesting that targeting FGFR4 may be a viable therapeutic strategy for cancer suppression." (PMID 41328353, 2026). "Notably, FGF19 is highly expressed in the luminal molecular subtype of breast tumors, and its levels are found to correlate with secretion from cancer cells." (PMID 41328353, 2026). "In addition, the expression of NCKAP5 and FGF19 is deregulated in specific histopathological types of human breast tumors." (PMID 23131872, 2012). "Finally, using a panel of well-validated tissue microarray, we show that a subset of primary breast tumors co-expresses FGFR4 and FGF19." (PMID 27192118, 2016). "Importantly, FGFR4, FGF19 and phospho-AKT were found to be co-overexpressed in a subset of basal-like breast tumors, suggesting that the FGFR4/FGF19 autocrine loop might be of clinical importance." (PMID 27192118, 2016). "HR+ breast tumors regardless of HER2 status (HR+/HER2+ and HR+/HER2−) were more likely to harbor CNAs in CCND1, FGF3, FGF4, and FGF19, which colocalizes in chromosome 11q13.3." (PMID 32695676, 2020).
cholangiocarcinoma (5 papers, 2016 to 2026). A carcinoma that arises from the intrahepatic biliary tree (intrahepatic cholangiocarcinoma) or from the junction, or adjacent to the junction, of the right and left hepatic ducts (hilar cholangiocarcinoma). "Prolonged exposure to elevated FGF19 levels may theoretically increase the risk of PSC patients for developing cholangiocarcinoma and other malignancies, as has been shown in mice." (PMID 27696157, 2017). "KLa has a role in inhibiting TGF-β1-induced EMT and FGF19/FGFR4 signaling induces EMT in cholangiocarcinoma." (PMID 29731962, 2018). "In cholangiocarcinoma cells, E-cadherin expression had a lower expression, whereas N-cadherin, Snail1 and Vimentin had higher expressions under FGF19 stimulation, indicating that FGF19 can trigger the EMT process." (PMID 26498355, 2016). "However, this tendency fade away when FGFR4 was knocked down, suggesting FGFR4 is required for the FGF19-induced EMT in cholangiocarcinoma cells." (PMID 26498355, 2016). "In disease state, FGF19 is critical for the development and progression of a number of cancers, including HCC, breast cancer, prostate cancer and cholangiocarcinoma." (PMID 26498355, 2016).
COVID-19 (5 papers, 2023 to 2024). A disease caused by infection with severe acute respiratory syndrome coronavirus 2. "In our study, higher steady-state levels of FGF19 were positively contributing to both analyzed outcomes, hospitalized COVID-19 and critical COVID-19." (PMID 38455043, 2024). "Less is known about connections between phenotypes of COVID-19 and the levels of FGF-19, EIF4EBP1, and Neurotrophin-3 (NTF3)." (PMID 38455043, 2024). "Indeed, it was reported that serum levels of the FGF19 protein were lower in asymptomatic than symptomatic COVID-19 patients." (PMID 38321133, 2024). "CCL23, among the other seven proteins (IL-17C, MMP-10, FGF-19, FGF-21, FGF-23, and CXCL5), was higher in asymptomatic COVID-19 patients than in patients with symptoms." (PMID 37834869, 2023). "A recent study determined that patients with asymptomatic SARS-CoV-2 infection had higher values of fibroblast growth factors (including FGF19, FGF21, and FGF23) compared to those with mild symptomatic COVID-19." (PMID 36828412, 2023). "Among them, serum levels of IL-10RB, FGF-19, and CCL-2 positively contributed to both hospitalized and critical COVID-19 conditions (OR: 1.10~1.16), while the other 4 proteins conferred risk on critical COVID-19 only (OR: 1.07~1.16), including EIF4EBP1, IL-7, NTF3, and LIF." (PMID 38455043, 2024).
Crohn ileitis (5 papers, 2016 to 2022). A Crohn disease involving a pathogenic inflammatory response in the ileum. "What causes a low FGF19 level in each case remains to be determined, but some cases of bile acid malabsorption begin acutely after an episode of ileitis, which is a common feature of bothSalmonella species andCampylobacter jejuni gastroenteritis." (PMID 27158477, 2016). "Decreased circulating FGF19 leading to excessive production of bile acids can be primary or secondary to bile salt malabsorption caused by ileal resection or ileitis." (PMID 27158477, 2016). "Besides, using a FGF19 cut-off <60 ng/L in a group of 466 patients with chronic diarrhea related to Crohn’s ileitis, FGF19 had a sensitivity and specificity of 80 and 68%." (PMID 35683489, 2022). "In this regard, “mRNA expression levels of ASBT, breast cancer-related protein (BCRP), sulfotransferase family 2A member 1 (SULT2A1), and fibroblast growth factor 19 (FGF-19) were significantly lower in inflamed regions in patients with active Crohn’s ileitis than in controls”." (PMID 32595517, 2020). "In the study, mRNA expression levels of ASBT, breast cancer-related protein (BCRP), sulfotransferase family 2A member 1 (SULT2A1), and fibroblast growth factor 19 (FGF-19) were significantly lower in inflamed regions in patients with active Crohn's ileitis than in controls." (PMID 30402511, 2018).
fibrosis (5 papers, 2013 to 2023). the formation of excess fibrous connective tissue in an organ or tissue in a reparative or reactive process. "Increased hepatic BA production and diarrhea, but not low FGF19, were associated with increased NAFLD fibrosis score, indicating dysregulation of the FXR-FGF19 axis and suggesting hepatic FGF19 resistance." (PMID 30682184, 2019). "As expected, FGF19 correlated negatively with C4 (rs -0.43, p<0.001) but neither FGF19 or C4 correlated significantly with the NAFLD fibrosis score or Fibroscan score." (PMID 30682184, 2019).